SERINC2 (serine incorporator 2)
Description:
Non-ATP-dependent, non-specific lipid transporter for phosphatidylserine, phosphatidylcholine, and phosphatidylethanolamine. Functions as a scramblase that flips lipids in both directions across the membrane. In contrast to SERINC3 and SERINC5, has no effect on HIV-1 particles infectivity.
Synonyms: TDE2L; FKSG84; PRO0899; TDE2
Tractability: Antibody: UniProt places it where antibodies can reach, with high confidence; its Gene Ontology location is reachable by antibodies, with high confidence; UniProt predicts a signal peptide or a membrane-spanning region; the Human Protein Atlas places it where antibodies can reach.
Gene: Protein-coding gene on chromosome 1 (31,409,565 to 31,434,680, forward strand). Ensembl gene ENSG00000168528.
Subcellular location: Cell membrane
Subcellular location (Human Protein Atlas): Plasma membrane; Nucleoplasm
Pathways (Reactome):
Metabolism: Serine metabolism
Gene Ontology:
Molecular function: phospholipid scramblase activity; acetyltransferase activator activity
Biological process: plasma membrane phospholipid scrambling; phosphatidylserine metabolic process
Cellular component: extracellular exosome; plasma membrane; membrane
Genetic constraint (gnomAD): Loss-of-function variants: 52 observed, 51.26 expected, observed/expected ratio (o/e) 1.01, 90% interval 0.81 to 1.28. The upper end of that interval is the gene's LOEUF score, 1.28, which puts it in group 5 of 6, group 1 being the genes least tolerant of losing a copy. Missense variants: 606 observed, 614.94 expected, observed/expected ratio (o/e) 0.99, 90% interval 0.92 to 1.05. Synonymous variants: 271 observed, 256.62 expected, observed/expected ratio (o/e) 1.06, 90% interval 0.95 to 1.17.
Homologues: Orthologues: chimpanzee SERINC2 (97% identical), pig SERINC2 (85% identical), dog SERINC2 (85% identical), guinea pig SERINC2 (84% identical), mouse Serinc2 (83% identical), rat Serinc2 (82% identical), rabbit SERINC2 (66% identical), tropical clawed frog serinc2 (60% identical), zebrafish serinc2 (59% identical), zebrafish serinc2l (58% identical), Drosophila melanogaster Serinc (40% identical), Caenorhabditis elegans Y57E12AL.1 (37% identical), and 1 more. Paralogues in human: SERINC1 (53% identical), SERINC3 (50% identical), SERINC5 (38% identical), SERINC4 (35% identical).
Diseases named in the same sentence as SERINC2 in open-access papers:
SERINC2 is named in the same sentence as 34 diseases in open-access papers, as found by Europe PMC text mining. Sharing a sentence is not in itself a finding about the gene and the disease. The quoted sentences say what the papers report.
lung adenocarcinoma (5 papers, 2020 to 2024). A carcinoma that arises from the lung and is characterized by the presence of malignant glandular epithelial cells. "For example, in lung adenocarcinoma, cell invasion, proliferation, and migration were suppressed by Serinc2 knockdown." (PMID 39417376, 2024). "Knockdown of SERINC2 inhibits the proliferation, migration, and invasion in lung adenocarcinoma." (PMID 32642801, 2020). "Knockdown of SERINC2 inhibits proliferation, migration, and invasion of lung adenocarcinoma." (PMID 32642801, 2020). "SERINC2 has previously been reported to be up-regulated in a variety of cancers and has been considered a biomarker after multiple bioinformatics analyses for early diagnosis or prognosis prediction in lung adenocarcinoma, ovarian cancer, and low-grade glioma (LGG)." (PMID 36612238, 2022). "Based on these findings, SERINC2 might be required for lung adenocarcinoma progression." (PMID 34943992, 2021). "Knockdown of Serinc2 inhibited cell invasion, migration, and proliferation via regulating the PI3K/AKT pathway in lung adenocarcinoma." (PMID 39417376, 2024). "Previous studies have shown that Serinc2 can inhibit the development of the lung adenocarcinoma through PI3K / Akt signaling pathway, and for the first time, we elaborated the protective effect of Serinc2 in acute lung injury from the perspective of Akt mediated apoptosis and inflammation." (PMID 35799194, 2022).
alcohol dependence (4 papers, 2017 to 2024). Physical and psychological dependence on alcohol. "SERINC2 has been associated with alcoholism, bipolar disorder and autism, but the comparability and specificity issues of the findings remain unaddressed." (PMID 39902246, 2024). "Further, the common SERINC2 variants and rare SERINC2 variant constellations have both been reported to be “specific” to risk for alcohol dependence in European descent among 12 diverse neuropsychiatric disorders." (PMID 39902246, 2024). "Followed by FDR correction, alcoholism was most significantly associated with SERINC2 variants in EAs (245 SNPs with 5.5×10-8≤p ≤ 0.049 and 4.9×10-5≤q ≤ 0.034)." (PMID 39902246, 2024). "Variants in the human orthologue of Serinc2 and Kcnn1 are strongly implicated in alcohol dependence." (PMID 34573345, 2021). "An alcoholism-risk allele was also found to decrease ICV, aligning with evidence of widespread brain shrinkage in alcoholism, supporting the hypothesis that this SERINC2 allele may increase the risk for alcoholism by reducing brain volume." (PMID 39902246, 2024). "As introduced above, we ever phenome-wide scanned a total of 49,268 subjects of European or African descent with 12 different neuropsychiatric disorders and reported that the common SERINC2 variants and the rare SERINC2 variant constellations were “specific” to alcoholism in European descent." (PMID 39902246, 2024). "Meanwhile, more other substance use disorders that usually are comorbid and share common pathogenesis with alcoholism were also significantly associated with SERINC2 variants in European descent, including cocaine dependence, marijuana dependence, nicotine dependence, and polysubstance dependence." (PMID 39902246, 2024). "The sharing of risk SERINC2 variants and their functional patterns among alcoholism, cocaine dependence, marijuana dependence, nicotine dependence, polysubstance dependence, schizophrenia, OCD, and autism may be interpreted by the high comorbidity rates among these diseases." (PMID 39902246, 2024). "These physiological functions support a potential role of SERINC2 in multiple neuropsychiatric, neurodegenerative and neurodevelopmental diseases such as alcoholism, bipolar disorder and autism." (PMID 39902246, 2024). "Three independent cohorts showed SERINC2 mRNA was differentially expressed in several other brains between alcoholism or schizophrenia and controls." (PMID 39902246, 2024). "Differential expression of SERINC2 mRNA in brains with alcoholism or schizophrenia." (PMID 39902246, 2024). "Finally, SERINC2 mRNA was differentially expressed in several brain regions between alcoholism or schizophrenia and controls." (PMID 39902246, 2024).
autism (2 papers, 2017 to 2024). Persistent deficits in social interaction and communication and interaction as well as a markedly restricted repertoire of activity and interest as well as repetitive patterns of behavior. "Additionally, one autism-risk allele decreased SERINC2 mRNA expression in cerebellar hemisphere and cortex (1.6×10-4≤p ≤ 0.020)." (PMID 39902246, 2024). "Additionally, we found that schizophrenia, OCD, and autism in European descent and bipolar disorder in Chinese were also significantly associated with SERINC2 variants, supporting the findings in literatures." (PMID 39902246, 2024). "Additionally, a much smaller number of SERINC2 variants was significantly associated with autism in EAs (rs10798856 and rs10158864: 2.0×10-7≤p ≤ 7.2×10-5 and 2.9×10-5≤q ≤ 5.3×10-3) and bipolar disorder in Chinese population (10 SNPs with 1.3×10-4≤p ≤ 4.7×10-4 and 0.025≤q ≤ 0.031)." (PMID 39902246, 2024). "SERINC2 is primarily linked to substance use disorders, schizophrenia, OCD, autism and bipolar disorder, not only statistically but also biologically." (PMID 39902246, 2024). "In summary, these findings indicate that SERINC2 is primarily linked to substance dependence, schizophrenia, OCD, autism and bipolar disorder, a conclusion that is supported by both statistical and biological evidence and published literatures." (PMID 39902246, 2024). "Therefore, our conclusion is that SERINC2 predominantly predisposes individuals to substance dependence, schizophrenia, OCD, autism and bipolar disorder, a conclusion supported not only by statistical evidence but also by biological findings." (PMID 39902246, 2024). "Because this gene have not been previously linked to autism, we proposed the SERINC2 gene as a novel ASD candidate gene." (PMID 28935972, 2017).
autism spectrum disorder (2 papers, 2017 to 2025). A spectrum of developmental disorders that includes autism, and Asperger syndrome. "Previously, SERINC2 was more reported in nervous system diseases such as bipolar disorder, autism spectrum disorder and alcohol dependence." (PMID 39897034, 2025).
bipolar disorder (2 papers, 2024 to 2025). A disorder of the brain that causes unusual shifts in mood, energy, activity levels and the ability to carry out day-to-day tasks. "In contrast, bipolar disorder-risk alleles down-regulated SERINC2 mRNA expression in the caudate, hypothalamus, and cerebellar hemisphere, while up-regulating it in the frontal cortex." (PMID 39902246, 2024). "The bipolar disorder-risk alleles decreased SERINC2 mRNA expression in caudate, cerebellar hemisphere and hypothalamus (0.007≤p ≤ 0.044) but increased it in frontal cortex (0.024≤p ≤ 0.027)." (PMID 39902246, 2024). "Following these studies, SERINC2 variants have also been associated to bipolar disorder (BP) in a Chinese population and autism spectrum disorder (ASD) in a Thai population." (PMID 39902246, 2024). "This supports the hypothesis that SERINC2 alleles may increase the risk for bipolar disorder by reducing caudate and pallidum GMVs." (PMID 39902246, 2024). "Significant associations between SERINC2 variants and bipolar disorder in Asian descent." (PMID 39902246, 2024).
cervical cancer (2 papers, 2024 to 2025). A primary or metastatic malignant neoplasm involving the cervix. "In this study, we uncovered that SERINC2 was a critical serine-associated gene and significantly upregulated in cervical cancer." (PMID 39897034, 2025). "Given the association of SERINC2 with serine metabolism, we aimed to investigate the necessity of serine for the growth of cervical cancer cells." (PMID 39897034, 2025). "Our study has indicated the association of SERINC2 and sphingolipid metabolism, which can be deemed as a promising target in cervical cancer therapy." (PMID 39897034, 2025). "As a serine transport associated protein, SERINC2 knockdown significantly reduced cervical cancer cells' intracellular serine level and altered the serine-associated-lipid metabolism." (PMID 39897034, 2025). "Subsequently, we detected the expression of SERINC2 in tumor samples from cervical cancer patients and confirmed the upregulation of SERINC2 protein expression in tumor." (PMID 39897034, 2025). "To further investigate the function of SERINC2 in cervical cancer, we applied siNC/siSERINC2 HeLa and C-4I cells for the subsequent experiments." (PMID 39897034, 2025). "In summary, the growth of cervical cancer cell lines relies on serine, and this dependency is mediated by SERINC2." (PMID 39897034, 2025). "We deduced that in cervical cancer, SERINC2 also played its role on membrane, regulating serine derived lipid such as sphingolipid and phosphatidylserine." (PMID 39897034, 2025). "Collectively, these findings suggest that SERINC2 systematically promotes cervical cancer tumorigenesis." (PMID 39897034, 2025). "Here, we identified serine incorporator 2 (SERINC2) as a critical gene which highly expressed in cervical cancer and negatively correlated with clinical outcomes." (PMID 39897034, 2025). "Initially, we were convinced that SERINC2 related to phosphatidylserine biosynthesis in cervical cancer cells." (PMID 39897034, 2025). "In this study, we investigated the functions of SERINC2 in cervical cancer through in vitro and in vivo experiments." (PMID 39897034, 2025). "We have discovered that SERINC2 increased serine intake and modulate lipid metabolism in cervical cancer." (PMID 39897034, 2025). "Functional exploration of SERINC2-mediated serine metabolism and nutrients competition unveil the mechanism of cervical cancer progression and T cell exhaustion." (PMID 39897034, 2025). "Collectively, SERINC2 showed higher expression in cervical cancer and correlated with poor prognosis, suggesting its importance in CESC development." (PMID 39897034, 2025). "To gain a deeper insight into the role of SERINC2 in cervical cancer progression, we firstly detected the mRNA and protein expression of SERINC2 in the cervical cancer cell line that preserved in our laboratory." (PMID 39897034, 2025). "SERINC2 promoted the progression of cervical cancer in vitro and in vivo." (PMID 39897034, 2025). "All in all, the understanding of SERINC2 may provide us with a new approach in cervical cancer immunotherapy." (PMID 39897034, 2025). "Besides, the growth of cervical cancer cells was found to be largely dependent on serine in a manner influenced by SERINC2." (PMID 39897034, 2025). "So far, the function of SERINC2 in cervical cancer remains unknown." (PMID 39897034, 2025). "All these evidences indicate the pivotal role of SERINC2 in TIME regulation and progression of cervical cancer." (PMID 39897034, 2025). "To delve deeper into the role of SERINC2 in the TIME, we utilized C-NKG mice grafted with human immune cells and cervical cancer cells to establish in vivo model." (PMID 39897034, 2025).
epilepsy (2 papers, 2021 to 2025). A brain disorder characterized by episodes of abnormally increased neuronal discharge resulting in transient episodes of sensory or motor neurological dysfunction, or psychic dysfunction. "MR analysis identified causal relationships, such as NBL1 in epilepsy, TPGS2 in ischemic stroke, and SERINC2 in VaD." (PMID 40624693, 2025). "Additionally, our MR analysis identified causal relationships between specific genes and disease outcomes, such as NBL1 in epilepsy, TPGS2 in ischemic stroke, and SERINC2 in VaD." (PMID 40624693, 2025).
glioma (2 papers, 2020 to 2024). A benign or malignant brain and spinal cord tumor that arises from glial cells (astrocytes, oligodendrocytes, ependymal cells). "The present study used data mining of the TCGA and GEO datasets to characterize the profiles of SERINC2 expression in glioma and investigated the association between the expression level of SERINC2 and OS in glioma." (PMID 32642801, 2020). "We created a PPI network using correlation genes with SERINC2 to investigate the underlying mechanisms involved in glioma tumorigenesis." (PMID 32642801, 2020). "However, in vivo and in vitro studies are urgently needed to further elucidate the underlying mechanism of SERINC2 in glioma oncogenesis." (PMID 32642801, 2020). "The present study used data mining of the TCGA and GEO datasets to examine the effect of SERINC2 expression on glioma patients’ survival and its potential regulation mechanism." (PMID 32642801, 2020). "The present study examined the function of the highly conserved molecule SERINC2 in glioma, and its correlation genes were investigated using bioinformatics analysis." (PMID 32642801, 2020). "The function of SERINC2 in tumors has been reported, but the role of SERINC2 in gliomas is not fully understood." (PMID 32642801, 2020). "In conclusion, our results support the important role of SERINC2 in glioma malignancy and LGG patient prognosis." (PMID 32642801, 2020). "Bioinformatics analysis was performed as the primary method to examine the function of SERINC2 and its correlated genes in glioma." (PMID 32642801, 2020). "To examine the protein levels of SERINC2 in different grade gliomas and normal brain tissues, we used IHC staining and protein expression scoring in the HPA to examine the level of SERINC2 protein expression in normal brain and glioma tissues." (PMID 32642801, 2020). "High Serinc2 expression is related to the shorter overall survival (OS) in low‐grade glioma, indicating that Serinc2 may be a potential prognostic marker." (PMID 39417376, 2024). "Our results suggested that aberrant SERINC2 expression existed in glioma and that its expression might be a potential prognostic marker in LGG patients." (PMID 32642801, 2020). "We further investigated the underlying mechanism of SERINC2 in glioma tumorigenesis and generated a list of positive and negative correlation genes with SERINC2 using Pearson correlation analysis." (PMID 32642801, 2020). "The present study used the RNA sequencing and microarray data from TCGA and GEO and IHC staining from the HPA and found that the mRNA and protein expression levels of SERINC2 were higher in glioma than in brain tissues and that GBM had the highest SERINC2 expression." (PMID 32642801, 2020). "Because of technological limitations, we could not further elucidate the underlying mechanisms of SERINC2 in the regulation of OS in LGG and glioma malignancy." (PMID 32642801, 2020).
leukemia (2 papers, 2020 to 2022). A malignant (clonal) hematologic disorder, involving hematopoietic stem cells and characterized by the presence of primitive or atypical myeloid or lymphoid cells in the bone marrow and the blood. "The upregulated lnc-eRNA SEELA enhances the chromatin occupancy of histone modifiers by directly interacting with K31 aa of histone H4, thereby promoting enhancer activity and SERINC2 expression to affect sphingolipid metabolism during leukemia progression." (PMID 33143730, 2020). "Our study revealed that the lnc-eRNA SEELA influences the biosynthesis of sphingolipids through SERINC2 to promote leukemia progression." (PMID 33143730, 2020). "In addition, mice in the sh-SEELA1 (P < 0.05), sh-SEELA2 (P < 0.05), and sh-SERINC2 (P < 0.01) groups survived longer than those in the control sh-NC group, showing that SEELA and SERINC2 affect leukemia progression in vitro and in vivo." (PMID 33143730, 2020). "The altered profile of sphingolipid metabolism in SEELA knockdown cells strongly resembled that in SERINC2 knockdown cells, further indicating that SERINC2 is the essential downstream effector of SEELA that influences sphingolipid synthesis and leukemia progression." (PMID 33143730, 2020).
non-small cell lung carcinoma (2 papers, 2022 to 2024). A group of at least three distinct histological types of lung cancer, including non-small cell squamous cell carcinoma, adenocarcinoma, and large cell carcinoma. "Tumor differentially expressed 2 (TDE2), also known as Serinc2, was first identified in non‐small cell lung cancer (NSCLC) cells, and TDE2 expression was higher in NSCLC samples." (PMID 39417376, 2024).
Papillary Thyroid Carcinoma (2 papers, 2022 to 2024). "The proliferation of papillary thyroid cancer TPC-1 cell lines was promoted after SERINC2 overexpression (p < 0.05)." (PMID 36612238, 2022). "SERINC2, one of the differentially methylated and expressed genes, was first identified as a potential tumor-driven indicator in papillary thyroid carcinoma." (PMID 36612238, 2022). "In conclusion, our results demonstrate the whole-genome DNA methylation and gene expression profiles of papillary thyroid carcinoma, identify SERINC2 as a potential tumor-driven biomarker, and preliminarily verify its function in PTC." (PMID 36612238, 2022). "In papillary thyroid carcinoma (PTC), Serinc2 expression is enhanced and Serinc2 may be a tumor‐driven indicator." (PMID 39417376, 2024).